LINC00974 (long independently transcribed non-coding RNA 974)
Gene: Long non-coding RNA gene on chromosome 17 (41,549,606 to 41,554,495, reverse strand). Ensembl gene ENSG00000226629.
Diseases named in the same sentence as LINC00974 in open-access papers:
LINC00974 is named in the same sentence as 7 diseases in open-access papers, as found by Europe PMC text mining. Sharing a sentence is not in itself a finding about the gene and the disease. The quoted sentences say what the papers report.
hepatocellular carcinoma (4 papers, 2014 to 2022). A malignant tumor that arises from hepatocytes. "Consistent withour study, evidence has confirmed that LINC00974 acts as an oncogenic factor toaccelerate proliferation and metastasis in hepatocellular carcinoma (Tang etal., 2014)." (PMID 35129574, 2022). "Interaction of hsa-mir-642a-5p and Linc00974 can increase the expression of keratin 19 and activate Notch and TGF-β signaling pathways, which will increase the proliferation and invasion of hepatocellular carcinoma." (PMID 29513728, 2018). "Based on this theory, we aimed to explore the regulatory mechanisms of Linc00974 and KRT19 (an lncRNA beyond the Flank10kb class with protein) when we first confirmed the aberrant expression in hepatocellular carcinoma in a previous study." (PMID 25476897, 2014).
ovarian carcinoma (2 papers, 2022). A malignant neoplasm originating from the surface ovarian epithelium. "As a result, they have shown upregulation of LINC00974 and HMGB2 mRNA expressions in ovarian cancer cells, while miR-33a expression (which directly targets HMGB2) was downregulated." (PMID 35907803, 2022). "So, silencing of LINC00974 by sponging miR-33a suppressed cell proliferation, invasion and EMT of cancer cells, suggesting the importance of LINC00974/miR-33a/HMGB2 axis in the progression of ovarian cancer." (PMID 35907803, 2022).
gastric carcinoma (1 paper, 2022). A carcinoma that arises from epithelial cells of the stomach. "Recently, LINC00974 expression has been reported to be increased in hepatocellularcarcinoma, gastric carcinoma, and oral squamous cell carcinoma." (PMID 35129574, 2022). "A previous study in human gastric carcinoma suggested thatupregulation of LINC00974 facilitates cell cycle progression." (PMID 35129574, 2022).
tumor (5 papers, 2014 to 2022). "Aberrant increased Linc00974 was detected in tumor tissues, indicating that Linc00974 was involved in the pathogenesis of HCC." (PMID 25476897, 2014). "To confirm the effect of Linc00974 downregulation on abdominal metastases, we conducted an intraperitoneal transplantation vaccination tumor model with nude mice." (PMID 25476897, 2014). "In conclusion, we identified a novel Linc00974 in human HCC that was upregulated due to hypomethylation in the promoter region of the tumor." (PMID 25476897, 2014). "In order to investigate whether Linc00974 correlated with HCC, we first detected the expression level of Linc00974 in tumor tissues and corresponding adjacent tissues." (PMID 25476897, 2014). "Finally, these findings beside expression validation by RT-qPCR, revealed LINC00974 as a novel index for clinical prognosis and diagnosis of tumor growth and metastasis, which can be evaluated as a potential therapeutic target in future studies of CRC targeted therapy." (PMID 35907803, 2022). "Both Linc00974 and KRT19 expression significantly correlated with decreased tumor differentiation grade (P<0.001), increased tumor size (P<0.001), and metastasis (P<0.001)." (PMID 25476897, 2014). "In conclusion, the combination of Linc00974 and KRT19 may be novel indices for clinical diagnosis of tumor growth and metastasis in HCC, while Linc00974 may become a potential therapeutic target for the prevention of HCC progression." (PMID 25476897, 2014). "For example, a Linc00974 antagonist might be developed for targeting upregulation of KRT19, which may be involved in tumor growth and metastasis." (PMID 25476897, 2014). "In addition, we discovered a plasma fraction of Linc00974 in the ROC curve analysis by binding Linc00974F-1 and CYFRA21-1, indicating a significant predication of tumor growth and metastasis of HCC." (PMID 25476897, 2014). "Therefore, both Linc00974 and KRT19 may be novel indices for clinical diagnosis of tumor growth and metastasis in HCC, while Linc00974 may also become a potential therapeutic target for the prevention of HCC progression." (PMID 26978351, 2016).
cancer (3 papers, 2014 to 2022). A tumor composed of atypical neoplastic, often pleomorphic cells that invade other tissues. "Moreover, LINC00974 also has been considered to be an oncogenic factor, It is, therefore, worthwhile to examine whether arctigenin exhibits an anti-cancer effect via regulation of LINC00974." (PMID 30884781, 2019). "Although the functional role of LINC00974 in the progression of CRC has not been reported yet, but the findings from several recent studies showed its key roles in the progression of different cancer types." (PMID 35907803, 2022).
LINC00974 also shares sentences with these, for which no sentence is quoted: fibrosis (1 paper); oral squamous cell carcinoma (1).